ATR (ATR checkpoint kinase)
Diseases named in the same sentence as ATR in open-access papers (continued):
Sharing a sentence is not in itself a finding about the gene and the disease.
cancer (continued). "In support of our results, inhibitors of ATR and DNK-PK kinases, the key players of the DDR, were shown to sensitize cancer cells to olaparib." (PMID 35646698, 2022). "Therefore, it is hypothesised that ALT+ cancers may display sensitivity to ATR inhibitors." (PMID 35326717, 2022). "Suppression of ATR induces genomic instability and thus activation of programmed cell death in ARID1A- cancer cells." (PMID 36249060, 2022). "PD-L1 upregulation in cancer cells has been observed, which is also a response to DSBs, and this process requires the activation of ATM/ATR/Chk1 kinases after IR or genotoxic treatment." (PMID 35130631, 2022). "Presumably, cancer cells exploit alterations of ATM/CHK2/p53to avoid cell cycle exit at the G1 phase and rely on ATR/CHK1/WEE1 activity to handle a high level of RS during continuous cell division." (PMID 36253861, 2022). "ATR is a key component of the targeted DNA damage response (DDR), a new cancer treatment pathway which has broad prospects for tumor selectivity." (PMID 36082941, 2022). "In response to the DNA damage by IR, cancer cells rapidly activate ATM, ATR, and DNA-PK, all of which are members of the phosphoinositide 3 kinase-related kinase family." (PMID 35328212, 2022). "Cancer-associated SPOP mutations impair Geminin K27-linked poly-ubiquitylation and lead to replication stress and cell death upon ATR kinase inhibition, implying that cancers with defective SPOP-Geminin signaling might be responsive to ATR inhibitors treatment." (PMID 35136173, 2022). "These tumours rely on ATR, CHK1 and also USP1 activity for their survival, suggesting that targeting USP1 would be an alternative strategy for treating cancers with high levels of MYC-induced replication stress." (PMID 36240066, 2022). "Aberrant activation of these DDR kinases (ATM, ATR, DNA-PK, CHK1, CHK2, and PARP) in cancer is strongly correlated with resistance to genotoxic cancer therapies, including in GB." (PMID 35406593, 2022). "In fact, tumor cells have developed mechanisms to deal with this basal replication stress, such as sustained activation of ATR and CHK1 kinases, and those mechanisms have been proposed to contain good targets for cancer therapy." (PMID 35969531, 2022). "In HR-proficient cancers, induction of synthetic lethality can be achieved through HRR inhibition by using specific inhibitors of ATM, ATR, Topoisomerase 2 or Bromodomain Containing 4 (BRD4) to create a BRCAness phenotype." (PMID 35328658, 2022). "The high ectopic expression of PRCC made cancer cells insensitive to DNA damage, and enhanced the heterogeneity of HCC cells by inhibiting the JNK/ATM/ATR/ATF2 axis." (PMID 34715922, 2021). "Initially, using 14 cancer cell lines (11 ALT+, 3 ALT−), Flynn and colleagues reported that an ATR inhibitor, VE-821, decreased the ALT phenotypes, including C-circles, APBs, and tSCEs, and selectively killed the ALT+ cells." (PMID 34069193, 2021). "The first strategy is the use of ATR inhibitors against ALT+ cell lines, which initially showed great promise as a potential targeted therapy for ALT cancers." (PMID 34069193, 2021). "In contrast, the combination of DUTi plus FUdR significantly enhanced cancer cell lethality with both ATM and ATR inhibition." (PMID 33824328, 2021). "This prompted us to investigate the role of the DDR pathway, and ATR specifically, in mediating TMZ resistance in MGMTlow/inhibited/MMRproficient models from various cancer types." (PMID 34676045, 2021). "Since CHK1 is the effector kinase of ATR, several cellular functions are shared between these kinases, and the rationales behind exploring CHK1 inhibitors for cancer therapy are hence similar to those for ATR inhibitors (Forment and O'Connor 2018)." (PMID 33888558, 2021).
cancer (continued). "Kinome data from the Cancer Dependency Map (DepMap) CRISPR and shRNA screens also support PDAC growth dependency on CHEK1 and ATR expression." (PMID 34852220, 2021). "Molecular inhibitors of ATM/ATR, for example, AZD1390 and VX-970, have been observed to result in both chemosensitivity and radiosensitivity in a wide range of cancer cells." (PMID 33431817, 2021). "The co-treatment prevented ATR-dependent feedback activation of CHK1 and hence increased the replication stress of cancer cells." (PMID 34201502, 2021). "Preclinical studies indicate that ARID1A mutant cancers display sensitivity to ATR inhibition while tumors without ARID1A mutations may be sensitive to Ataxia telangiectasia and Rad3 related (ATR) inhibitors in combination with poly-ADP ribose polymerase (PARP) inhibitors." (PMID 34518240, 2021). "In this analysis, we only considered genes that were affected in at least four TCGA cases within a cancer type and therefore only seven genes (BRCA1/2, ATM, ATR, PALB2, CHEK2, BRIP1) were included." (PMID 34572800, 2021). "Treatment with the combination of AZD6738, an inhibitor of ATR, and olaparib significantly improved ionizing radiation-induced resistance, suggesting that combination therapy with two or more agents might be an effective approach for treating cancers intrinsically resistant to radiation." (PMID 34238917, 2021). "The ATR/p62 signaling pathway is also critical for HPV viral replication and likely contributes to progression to cancer." (PMID 34578402, 2021). "Possibly, regarding this phenomenon, the same gene has opposite prognostic functions in different cancers; however, gene methylation was inversely correlated with expression in most cases, expect for RAD1, ATR, and ATM." (PMID 34869316, 2021). "Given that the ATR/CHK1 signaling pathway has been proved to play a significant role in DNA damage repairment (DDR) and resulte in cancer chemoresistance." (PMID 34474677, 2021). "Combining PARP and ATR inhibitors, or CHK1 and WEE1 inhibitors are efficient strategies for cancer stem cells sensitization." (PMID 34359720, 2021). "In this work, we study the effects of an anti-cancer drug, namely AZD6738, that works by inhibiting ATR activity." (PMID 34459993, 2021). "There are several studies showing the potential of combination therapy based on irradiation and various DDR inhibitors (DNA-dependent protein kinase (DNA-PK), ATM/ATR, LIG4, PARP1, CHK1) but mainly in other types of cancer." (PMID 32605254, 2020). "On the other hand, targeting DDR enhances the therapeutic effects of anti-cancer chemotherapy, which led to the development of specific kinase inhibitors for ATM, ATR and DNA-PKcs." (PMID 32015826, 2020). "Depletion of FANCD2 protein expression significantly suppresses the cancer cell proliferation and tumor colony formation and metastasis potential, as well as cell cycle progression, by involving cyclin-CDK and ATR/ATM signaling." (PMID 32906798, 2020). "For example, the dependence of many cancer cells specifically on the G2/M checkpoint has led to the development of agents that target this checkpoint, particularly Chk1, Wee1, ATM, and ATR." (PMID 32117972, 2020). "Because elevated genome instability is caused by MRS after WRNIP1 depletion in cells with dysfunctional ATR checkpoint, these findings could contribute to understanding how cells handle replication–transcription conflicts to eventually avoid early-onset of human diseases and cancer." (PMID 32046194, 2020). "The kinome profiling with KSEA and PTM-SEA further indicated cancer-specific activation of kinases in DDR signaling, such as ATM and ATR (bold font), which agreed to the results of the initial phosphoproteomic analysis." (PMID 32089736, 2020).
cancer (continued). "We asked next, how general is the correlation between FOXM1 expression and markers for replication stress (pS345 Chk1 and/or pS428 ATR) and FOXM1 transcriptional targets Cyclin B and RAD51 in cancer cell lines and tumor samples." (PMID 33253193, 2020). "Accumulating evidence demonstrated that aberrant activation of DDR proteins (ATM, ATR, DNA-PK, Chk1, Chk2 and PARP) in cancer is strongly correlated with resistance to genotoxic anti-tumor therapeutics of cancer cells." (PMID 32664581, 2020). "Cell cycle checkpoints, e.g., ATR and CHK1 are active therapeutic targets in numerous cancers including HGSOC either as a monotherapy or as a sensitizer of DNA damaging drugs and radiation therapy." (PMID 32647134, 2020). "We compared the antitumour efficacy of the combination of ionising radiation (IR) with two DNA damage response inhibitors, the PARP inhibitor olaparib and the ATR inhibitor AZD6738 (ceralasertib), in subcutaneous versus orthotopic cancer models." (PMID 32546832, 2020). "Increasing evidence has indicated that synthetic lethality using ATR, CHK1, or Wee1 inhibitors can be used to exploit oncogene-induced RS in cancer." (PMID 31362335, 2019). "Inactivating Rad51 in the homologous recombination repair (HR) pathway led to differential sensitivity of MCF-7 and Hela cells to ATR and CHK1 inhibitors, implicating ATR and CHK1 as potential drug targets for HR-defective cancers." (PMID 31018854, 2019). "Thus, inhibiting the ATR-Chk1 pathway may induce cancer-specific synthetic lethality." (PMID 31805725, 2019). "Cell death induced by ATR inhibition is highly selective for ALT+ cells, suggesting ATR inhibitors as potentially useful in the treatment of ALT+ cancers." (PMID 30871494, 2019). "Taken together, these results indicate that genotoxic stress induces the Oct-6 expression and DNA binding activity in cancer cells via the generation of ROS and DDR/ATR activation-dependent mechanisms." (PMID 31212703, 2019). "Loss of SFPQ drives RNA:DNA-hybrid formation, impaired replication and results in dramatically increased recombination frequencies in the context of ATR phosphorylation at telomeres of telomerase-positive and ALT cancer cells." (PMID 30824709, 2019). "In this study, we found that forced mitotic entry upon ATR inhibition potentiates cytotoxic effects of PARP inhibition using olaparib in BRCA2‐depleted and Brca2 knockout cancer cell line models." (PMID 31529615, 2019). "Investigation on cell cycle checkpoint signaling through ATM/ATR and pathways involved in cancer onset and progression has led to discover potent and selective ATM/ATR inhibitors that are actually in preclinical and clinical development, respectively." (PMID 29770165, 2018). "It is possible that in these cancer cells, there is altered expression or activity of DSB signaling molecules such as ATM or ATR, which makes these cells particularly sensitive to VX-984-mediated DNA-PKcs inhibition." (PMID 29899825, 2018). "A literature and COSMIC search revealed that several of these mutations have been detected in other model systems and other cancer subtypes, e.g. PARP-1 (V377S), ATR (K297 N), FANCA (G809 N), and MLH3 (I541V)." (PMID 30305041, 2018). "As well, ATR and CHK1 inhibitors have shown selective cytotoxic effects on Cyclin E1 (CCNE1) overexpressing cancer due to the high dependency of these tumors on the ATR/CHK1 axis." (PMID 30466442, 2018). "Several ATR and ATM inhibitory compounds have been explored as therapeutic alternatives for cancer treatment, either as chemo- or radiosensitizers, or individually through synthetic lethality." (PMID 30265735, 2018).
cancer (continued). "Among the 27 somatic mutations, 24 were restricted to the brain metastases, of which 4 affected cancer-related genes (i.e., FGFR2, MAP2K4, ATR and PIK3CA)." (PMID 29755676, 2018). "A more potent ATR inhibitor, VE-822 (VX970), was recently developed and radiosensitised cancer cells in vitro and in vivo." (PMID 29757235, 2018). "We provide a new solution to a subtyping of cancer patients with dominant ATR/HSP90 expression by combining inhibitors of ATR-Chk1, HSP90, or Cdc7 in cancer combination therapy." (PMID 29209046, 2017). "One important implication for our discovery of spDSB-induced tumorigenicity and cancer cell stemness pathway is translational: it provides a strong, mechanism-based rationale for targeting the ATM/ATR pathway in cancer treatment." (PMID 28337983, 2017). "Interesting targets to overcome these cancer defense mechanisms are: PARP, DNA-PK, PI3K, ATM, ATR, CHK1/2, and WEE1 inhibitors." (PMID 29113422, 2017). "In this paper, we unveiled a novel role of Cdc7-Dbf4 in the regulation of ATR/ATM checkpoint signaling and HR DNA repair in cancer by phosphorylating HSP90 at S164." (PMID 29209046, 2017). "For example, specific ATR inhibitors (VE-821 and NU6027) were shown to enhance cytotoxicity of cancer cells in combination with multiple DNA damaging agents." (PMID 28558031, 2017). "Activity of a second ATR inhibitor, AZD6738 (AstraZeneca, UK), is currently being examined in a Phase I clinical trials for advanced cancer." (PMID 29069866, 2017). "Both ATR and CHK1 inhibitors as single agents exploit the specific molecular pathologies of cancer, in particular the high levels of replication stress resulting from activated oncogenes." (PMID 28448462, 2017). "ATR and CHK1 are clearly good targets for the selective sensitisation of cancers to conventional therapy." (PMID 28448462, 2017). "It has also been reported that ATR- and CHK1 inhibitors display synergistic activity in cancer cells." (PMID 29138515, 2017). "Among the top candidates include ATR, CHK1, WEE1 and several other genes, some of which are involved in DNA replication, cell cycle, DNA repair and cancer formation." (PMID 28262781, 2017). "As p97 is a druggable target, p97 inhibition in the context of DDR has great potential for cancer therapy, as shown for other DDR components such as PARP, ATR and CHK1." (PMID 28847819, 2017). "Our joint analysis of MSI-H tumours from multiple cancer types has revealed that several DNA repair pathways other than MMR, including ATR, BER, HR and NHEJ, are altered by single-nucleotide and MS mutations." (PMID 28585546, 2017). "In present study we present a novel function of excess Cdc7-Db4 in overriding replication stress to promote cancer cell survival and tumorigenesis by the phosphorylation of HSP90-S164 that enhances the ATR/ATM-mediated signaling and HR DNA repair." (PMID 29209046, 2017). "Indeed, it is known that ATR and Chk1 suppress the apoptotic response following DNA replication stress, and that tumors characterized by elevated levels of replicative stress, such as Myc-driven cancers, are extremely vulnerable to the pharmacological targeting of G2/M checkpoint kinases." (PMID 26930412, 2016). "In this context, the identification of cancers presenting high levels of RS is important to guide the use of ATR and CHK1 inhibitors in cancer therapy." (PMID 27577084, 2016). "Phosphorylated forms of ATR (PS428-ATR) and ATM (PS1981 ATM) are expressed in cancer cells as a result of DNA damage." (PMID 27220670, 2016).
cancer (continued). "Inhibition of aberrantly active DDR signaling pathway has become an attractive therapeutic strategy in cancer therapy with highly selective small molecule inhibitors of ATM and ATR signaling in preclinical and clinical development, respectively." (PMID 27391441, 2016). "Response of cancer cells to chemotherapy-induced DNA damage is regulated by the ATM-Chk2 and ATR-Chk1 pathways." (PMID 26544894, 2015). "ATR (located on human chromosome 3q22-q24) and TOPBP1 (located on human chromosome 3q22.1) are co-amplified in 11 carcinomas." (PMID 26438152, 2015). "Certainly, amplification of ATR and TOPBP1 has been separated in other carcinomas and the trend in the TCGA database is towards inactivation of ATM kinase signaling and increased ATR kinase signaling." (PMID 26438152, 2015). "These opposing effects on cancer progression are controlled by two different branches of DDR signaling, respectively ATM/CHK2 and ATR/CHK1." (PMID 22373487, 2012). "It is also likely, that the genetic make up of a particular subset of cancer cells influences their relative sensitivity to ATM and/or ATR inhibitors." (PMID 19903334, 2009). "In this study, we have observed that in contrast to the ATM selective inhibitor KU55933, ATM/ATR dual inhibitors such as caffeine and CGK733 can suppress cyclin D1 levels in cancer cell lines." (PMID 19903334, 2009). "Observations on cancer cell proliferation and survival based on the use of ATM/ATR inhibitors should thus be interpreted with caution." (PMID 19903334, 2009). "Various proteins that associate with centrosomes such as pericentrin, STK15/BTAK/Aurora-A kinase, ATR, BRCA1, BRCA2, have been shown to influence centrosome duplication in human cancer." (PMID 17081288, 2006). "These patented compounds collectively highlight a growing trend in ATR, ATM and DNA-PK targeted cancer therapies, with increasing emphasis on combination approaches, improved drug delivery methods, and multi-targeted kinase inhibition to enhance treatment efficacy and overcome resistance mechanisms." (PMID 40256842, 2025). "Also, ATM, ATR, and TP-53 genes were downregulated with NaB treatment in COLO-205 cancer cell lines." (PMID 40872562, 2025). "This synthetic vulnerability of cancer cells, particularly those already experiencing high levels of RS or defective DDR pathways, underpins the therapeutic rationale for ATR inhibitor monotherapy or combination regimens that further destabilize replication processes." (PMID 40869030, 2025). "To explore the role of AEP in genotoxic tolerance in cancer, we investigated whether BC patients expressing different protein levels of AEP and ATR presented differences in the radiotherapy response." (PMID 40012043, 2025). "Many cancers exhibit defects in DDR, making them more reliant on ATR/Chk1 or ATM/Chk2 for survival." (PMID 40422251, 2025). "This seems to constitute a common strategy used by cancer cells to deal with RS without hyperactivating the ATR pathway and checkpoint response, which would be detrimental for tumor growth." (PMID 41009395, 2025). "Preclinical studies indicate that ATR inhibitors, including VE‐821, berzosertib, and AZD6738, may act as radiosensitizers in various cancer types." (PMID 40859871, 2025).